PARP1 (poly(ADP-ribose) polymerase 1)
Diseases named in the same sentence as PARP1 in open-access papers (continued):
Sharing a sentence is not in itself a finding about the gene and the disease.
glioma (continued). "Moreover, it has been demonstrated that PARP1 is upregulated as glioma malignancy increases, and its increased representation in tumor cells allows these cells to repair damaged DNA sequences during their active division." (PMID 39598347, 2024). "Because over-activated PARP1 contributes to DPT-induced glioma cell death, we tested whether PARP1 could regulate TAX1BP1 distribution to mitochondria." (PMID 37186123, 2023). "Present study was purposed to figure out the expression level of mitochondrial sirtuins (SIRT3, SIRT4, SIRT5) and related genes (GDH, OGG1-2α, SOD1, SOD2, HIF1α and PARP1) in 153 glioma tissue samples and 200 brain tissue samples from epilepsy patients (taken as controls)." (PMID 36809279, 2023). "To clarify why over-activated PARP1 could promote TAX1BP1 distribution to mitochondria, we tested the role of NAD+ in DPT-induced glioma cell death considering that it is a substrate of activated PARP1." (PMID 37186123, 2023). "In conclusion, we demonstrated that the NAD+ depletion caused by PARP1 overactivation resulted in mitochondrial translocation of TAX1BP1, which contributed to DPT-induced nuclear translocation of AIF and glioma cell parthanatos via upregulation of mitochondrial complex I activity and assembly." (PMID 37186123, 2023). "In this study, RNA-seq data of 639 glioma samples were downloaded from the GEO (Gene Expression Omnibus) database and divided into PARP1_H and PARP1_L according to the front and rear thirds of the expression level of PARP-1." (PMID 36092717, 2022). "PARP-1 was proved an effective target for glioma therapy based on the results above." (PMID 36092717, 2022). "In conclusion, this study investigated the effect of PARP-1 on glioma prognosis and the sensitization effect of radiotherapy and chemotherapy, established a novel nomogram to evaluate the overall survival of glioma patients, and further explored targeted therapy for glioma." (PMID 36092717, 2022). "It is reported that PARP1 status is positively correlated with the degree of glioma malignancy." (PMID 35806303, 2022). "RNA-seq data of 639 glioma samples were downloaded from the GEO (Gene Expression Omnibus) database and divided into PARP1_H and PARP1_L according to the front and rear thirds of the expression level of PARP-1." (PMID 36092717, 2022). "In particular, PARP-1 is highly expressed in several types of cancers, including glioma." (PMID 32170186, 2020). "Notably, cleaved Poly(ADP-ribose) polymerases (PARP1) activity, which is shown to be activated by DNA damage was also elevated in glioma cells in the co-culture condition as confirmed by ELISA assay." (PMID 31216715, 2019). "Increased PARP1 levels show a positive correlation with increasing tumor grades in Gliomas." (PMID 31119097, 2019). "Moreover, the correlations between PARP1 and three routinely used glioma markers detected by IHC were also tested in a clinical GBM cohort." (PMID 28654422, 2017). "Thus, the current study is designed to investigate expression level of SIRT3, SIRT4, SIRT5 and associated genes SOD1, SOD2, OGG1-2α, PARP1, GDH and HIF1α in glioma patients and to find out whether this expressional deregulation effects the risk of glioma." (PMID 36809279, 2023). "Thus, NAD+ depletion contributed to PARP1-triggered nuclear translocation of AIF in glioma cells." (PMID 37186123, 2023). "The inhibition of PARP1 together with temozolomide may overcome the acquired resistance of GBM cells on temozolomide which also counteracted gliomagenesis by inducing mitotic catastrophe and homologous recombination repair deficiency in PTEN‐mutant glioma." (PMID 37491836, 2023). "Additionally, PARP-1 was proved an effective target for glioma therapy." (PMID 36092717, 2022).
glioma (continued). "This is consistent with recent reports that glioma cells are defective in NAD+ biosynthesis, especially for those with IDH1 somatic mutations and suggests a major factor in the regulation of PARP1 signaling in GSCs and glioma cells may be related to a defect in NAD+ biosynthesis." (PMID 34806016, 2021). "Finally, to investigate whether this effect could also be observed in tumour progression in vivo, we used a preclinical glioma model generated by inoculation of either Parp1+/+ cRb−/− RasV12 or Parp1−/− cRb−/− RasV12 glial cells in mice." (PMID 33050515, 2020). "Furthermore, upon transfection of wild-type PTEN into PTEN-deficient glioma cells (U138MG and U87MG), caspase-3 activation, cleavage of PARP-1, and nucleosomal ladder pattern of DNA fragmentation were observed, and these characteristics gradually increased on the 7th and 9th day after transfection." (PMID 32565808, 2020). "In follow-up studies, we will further investigate the effects of other PARP1 inhibitors in the context of our research and plan to validate and extend our current findings using natural H3K27M-mutant glioma models." (PMID 40661778, 2025). "further highlight the prognostic relevance of PTMs in glioma, demonstrating that stearoyl‐CoA desaturase (SCD) regulates DNA damage repair by modulating PARP1 activity—a process dependent on PARP1's PTM." (PMID 40090864, 2025). "Inhibition of PARP1 restores GSCs sensitivity to TMZ,233 enhances glioma‐initiating cell sensitivity to radiation, and inhibits glioma‐initiating cell growth, self‐renewal, and DNA damage repair." (PMID 37576862, 2023). "In summary, we found in the present study that DPT induced PARP1 over-activation and TAX1BP1 distribution to mitochondria in the glioma cells in vitro and in vivo." (PMID 37186123, 2023). "We showed that treatment with DPT (450 nM) induced PARP1 over-activation and Tax1 binding protein 1 (TAX1BP1) distribution to mitochondria in human U87, U251 and U118 glioma cells." (PMID 37186123, 2023). "PARP-1 (Poly ADP-ribose polymerase 1) is a hot spot for cancer-targeted therapy and was reported to be significantly elevated in glioma." (PMID 36092717, 2022). "Further, the cytotoxic and DNA damage effect of the IR+PARGi combination was strongly suppressed by pre-treatment with the PARP1/PARP2 inhibitor ABT-888 (PARPi; Veliparib, 10 μM) in several GSCs as well as the model glioma cell line, LN428." (PMID 34806016, 2021). "We have previously demonstrated the radiosensitising properties of the poly(ADP-ribose) polymerase-1 (PARP-1) inhibitors olaparib and rucaparib in neuroblastoma and glioma cells, where they act principally by preventing repair of radiation-induced damage." (PMID 34011385, 2021). "Caffeine induces glioma cell death, possibly via elevating the cleaved PARP-1/PARP-1 ratio and AIF expression." (PMID 34684653, 2021). "Deoxypodophyllotoxin (DPT), a natural chemical, has been reported to induce parthanatos in glioma cell lines and mice models of xenograft glioma, which can be inhibited by antioxidant N-acetyl-L-cysteine (NAC) and PARP1 inhibitor 3AB." (PMID 33665167, 2020). "Other experiments were aimed at investigating the involvement of the parthanatos pathway, a PARP-1-dependent cell death mechanism, in AEBP1-depleted U138MG glioma cells." (PMID 32565808, 2020). "Rhaponticum carthamoides transformed root extract induces double strand DNA damage by increasing the number of phosphorylated H2A.X- and cleaved PARP1-positive U87MG cells and patient-derived IV grade glioma cells." (PMID 30171426, 2018). "As reported in pediatric glioma SF188 cells, BI2536, a PLK1 inhibitor, induced apoptosis determined by PARP‐1 cleavage in A172 cells." (PMID 30221846, 2018).
glioma (continued). "In order to obtain data concerning the number of cells expressing the apoptosis marker, i.e. cleaved Poly ADP-Ribose Polymerase 1 (PARP1), flow cytometry analysis was performed on both U87MG cell line and grade IV glioma cells." (PMID 29786770, 2018). "In case of SIRT3 (p = 0.0142) and HIF1α (p = 0.0385) significant upregulation was observed while non-significant upregulated expression was observed in PARP1 (p = 0.203) in glioma samples as compared to healthy samples." (PMID 36809279, 2023). "Recently, a study found that the expression level of PARP-1 mRNA in glioma cell lines was significantly increased, suggesting that PARP-1 is expected to become a new prognostic indicator for glioma patients and a new anti-glioma therapy target." (PMID 36092717, 2022). "Another PARP-1 inhibitor, talazoparib, increased DNA damage and PARP–DNA trapping, enhancing cytotoxicity against EGFR-amplified glioma sphere-forming cells, Additionally, it reduced tumor growth significantly in EGFR-amplified subcutaneous models but not in nonamplified models." (PMID 35873570, 2022). "While there are many significant gene expression differences among the two major subtypes of glioma stem cells (GSCs) (Proneural, PN; Mesenchymal, MES), as we have described, the expression of PARP1 is seen as a major genotypic difference when comparing astrocytes to both types of GSCs (PN and MES)." (PMID 34806016, 2021). "Elevated expression of the DNA damage response proteins PARP1 and poly(ADP-ribose) glycohydrolase (PARG) in glioma stem cells (GSCs) suggests that glioma may be a unique target for PARG inhibitors (PARGi)." (PMID 34806016, 2021). "Moreover,we also tested the effect of PTE on apoptosis-related proteins (including Caspase 3 and 9, PARP-1, Bax, Bcl-2 and Survivin) after treated for 24 h, 48 h, 72 h in T98G and LN18 glioma cells." (PMID 33737656, 2021). "Blank NLCs, despite not inducing cytotoxicity, were able to make glioma cell cultures more sensitive to apoptosis, exercising a down-regulation of Blc-2, suppressing PARP-1 dependent repair and blocking cellular proliferation." (PMID 32170186, 2020). "Interestingly, the drug targets identified in this study include PARP1, for which there is an active phase II clinical trial testing PARP-inhibitor Veliparib (ABT-888) in combination with radiotherapy and temzolomiode for H3 WT high-grade glioma (NCT03581292)." (PMID 37637064, 2023). "Therefore, we used DPT in this study to trigger glioma cell parthanatos and investigated whether TAX1BP1 is a downstream signal of activated PARP1 and initiates nuclear translocation of AIF via activation of respiratory complex I." (PMID 37186123, 2023). "Although hereditary DNA repair defects (involving the BRCA genes) have not been described to play a role in gliomas, downregulation or pharmacologic inhibition of HR or PARP-1 may be a reasonable strategy, notably for MGMT-expressing tumors." (PMID 38068493, 2023). "Moreover, the levels of p-ATM, p-H2AX, PARP1 and PAR were all increased in DPT-treated gliomas." (PMID 37186123, 2023). "Glioma tumors, glioma-derived cells and particularly GSCs are thought to be resistant to DNA damage treatment due to increased expression of the DNA repair machinery and of select DNA damage response (DDR) genes, including PARP1, a critical DNA damage sensor and DNA repair coordinator." (PMID 34806016, 2021). "However, in this study, we found that oxaliplatin can induce overactivation of PARP1, leading to release of AIF, and then AIF interacted with MIF and was transferred into the nucleus, resulting in parthanatos in OSCC cells, which is similar to a previous study on gliomas." (PMID 33495407, 2021).
gastric cancer (69 papers, 2013 to 2026). A primary or metastatic malignant neoplasm involving the stomach. "Genetic variations in PARP-1 have also been associated with an increased risk of gastric cancer, further supporting its potential as a biomarker for the disease." (PMID 41004487, 2025). "CircDIDO1 induces apoptosis in gastric cancer cells by encoding DIDO1 protein isoform which interacts with the poly ADP-ribose polymerase 1(PARP1) protein to inhibit its DNA repair ability." (PMID 35936754, 2022). "One study in gastric cancer patients showed that high PARP-1 expression was associated with poor prognosis, but only in patients with a more advanced disease stage." (PMID 33572586, 2021). "In patients with gastric cancer, high PARP1 expression is shown to be associated with increased depth of tumor invasion and lymphatic invasion." (PMID 33133138, 2020). "H. pylori infection activates other BER proteins, such as PARP1 and enhances the inflammatory response, suggesting that the bacterium modulates the host PARP1 status to drive inflammation-associated gastric cancer." (PMID 30249046, 2018). "The PARP1 rs1136410 synergistically interacted (ORinteraction = 1.84) with XRCC1 rs25487 encoding p.Arg399Gln in gastric cancer risk." (PMID 27588484, 2016). "Susceptibility to gastric cancer is associated with PARP1 rs1136410 encoding p.Val762Ala, along with the Ala variant, which displayed diminished enzymatic activity." (PMID 27588484, 2016). "Evaluation of PARP-1 cleavage and caspase-3 cleavage as markers of induction in apoptosis revealed that in gastric cancer cells nab-paclitaxel, oxaliplatin and epirubicin treatment caused an increase in the expression of both cleaved PARP-1 and caspase-3." (PMID 23460921, 2013). "In the subgroup analysis by cancer type, the PARP1 Ala genotype was significantly associated with gastric cancer and brain tumor which may be ascribed to the cancer specificity and sample size." (PMID 24489833, 2014). "In addition, by performing tissue microarrays on the 166 cases of gastric cancer patients, we could observe that the expression status of PARP1 and FOXO3A were significantly associated with overall survival (OS) and relapse-free survival (RFS)." (PMID 26540566, 2015). "Thus, we could suggest that PARP1 expression is associated with aggressive phenotypes while FOXO3A expression is associated with less aggressive phenotypes of gastric cancers." (PMID 26540566, 2015). "This modification stabilizes PARP1, enhances DNA repair, and promotes oxaliplatin resistance, advancing our understanding of drug resistance mechanisms in gastric cancer." (PMID 41228380, 2025). "Although there are no reports of parthanatos or PRG in STAD, evidence suggests that its key regulator, PARP-1, plays a role in gastric cancer progression and drug resistance." (PMID 41004487, 2025). "It has been demonstrated that inhibiting PARP-1 activity enhances the chemosensitivity of cisplatin-resistant gastric cancer cells." (PMID 41004487, 2025). "Targeting PARP-1 has shown promise in overcoming resistance, as the combination of the DNA repair inhibitor ailanthone with a PARP-1 inhibitor synergistically suppresses tumor growth in gastric cancer." (PMID 41004487, 2025). "In gastric cancer stem‐like cells, METTL3 upregulation is responsible for PARP1 overexpression which is associated with oxaliplatin resistance due to DNA damage repair." (PMID 39661414, 2024). "From a molecular point of view, NSC305787 induces apoptosis markers (cleaved PARP1) and DNA damage (γH2AX) in the evaluated cervical and gastric cancer cell models." (PMID 38972247, 2024). "Some PARP1 inhibitors have been put into the clinic for cancer treatment, including breast, ovarian, and gastric cancers." (PMID 38475878, 2024). "M6A methyltransferase METTL3 has been reported to contribute to oxaliplatin resistance by stabilizing PARP1 mRNA in CD133 + gastric cancer stem cells." (PMID 39731162, 2024).
gastric cancer (continued). "Previous studies have reported that TOP2A is characterized by PARP-1 cleavage and caspase-3 activation in gastric cancer, thus triggering the apoptosis pathway." (PMID 37781045, 2023). "PARP1 is mostly over-expressed in cancers, but in the work low PARP1 expression level was found in the clinical samples from the patients with gastric cancer." (PMID 36982223, 2023). "METTL3 facilitated oxaliplatin resistance via enhancing the stability of PARP1 mRNA in gastric cancer stem cells." (PMID 36003776, 2022). "In gastric cancer patients with a BRCA1 gene alteration (mutation or CNA), high PARP1 expression was demonstrated to be associated with a significantly poorer OS compared to patients with low PARP1 expression." (PMID 34440228, 2021). "We further analyzed the expression levels of PARP1 and PDL1 in groups with different DDR gene mutations and MSI and TMB status, by using TCGA gastric cancer cohort." (PMID 33960179, 2021). "For instance, gastric cancer patients with higher PARP1 expression level had significantly shorter overall survival and disease-free survival." (PMID 33112558, 2020). "Especially, suppression of PARP1 inhibited gastric cancer cells by inducing tumor suppressor FOXO3A." (PMID 27643881, 2016). "PARP-1 promotes tumor angiogenesis, and elevated expression of PARP-1 is found in various cancers including breast, prostate, pancreatic and gastric cancer." (PMID 26934315, 2016). "Similar to Olaparib, knock-down of PARP1 by siRNA significantly inhibited the proliferation and colony formation of gastric cancer cells." (PMID 26540566, 2015). "In terms of therapy resistance, PARP-1 contributes to chemotherapy resistance in gastric cancer." (PMID 41004487, 2025). "In addition, targeting the PARP1 likely stimulate innate immune signaling to promote immune based therapy in gastric cancer." (PMID 41568291, 2025). "Moreover, studies with oxaliplatin sensitive and resistant gastric cancer organoids revealed that CD133+ CSCs acquire resistance through METTL3-mediated m6A modification of PARP1 mRNA." (PMID 41228380, 2025). "It has also been shown that miR-103a could suppress the cell growth, migration, and invasion of gastric cancer, and miR-103a-2-5p could target PARP-1 to inhibit colony formation and cell survival." (PMID 38486250, 2024). "Moreover, research on gastric cancer has demonstrated that PARP1 can control tumour growth via the NF-κB pathway." (PMID 38388665, 2024). "Furthermore, a diminished expression of PARP-1, a DNA damage response (DDR)-associated protein, has been identified as a prognostic indicator for patients with stage 2 and 3 gastric cancer." (PMID 38817897, 2024). "PARP-1 inhibition impairs DNA damage repair and induces apoptosis in gastric cancer cells." (PMID 35936754, 2022). "We identified that the induction in caspase-3 and PARP-1 activation via TPD52L2 silencing might be a reason for the apoptotic-induced antitumor effect in gastric carcinoma cells (OXA resistant)." (PMID 35087592, 2022). "Furthermore, PARP1 was demonstrated to promote proliferation in gastric cancer cell lines, thought to be a result of FOXO3A-mediated cell cycle arrest suppression." (PMID 34440228, 2021). "In order to clinically verify the importance of PARP1 in the recurrence of gastric cancer after curative surgery and adjuvant chemotherapy, we enrolled gastric cancer patients undergoing adjuvant chemotherapy in Sun Yat-sen University’s Gastric Cancer Research Center." (PMID 34497808, 2021). "Our study found that PARP1 inhibitors in combination with oxaliplatin have a powerful anti-tumor effect in gastric cancer patients without BRCA1 mutations." (PMID 34497808, 2021). "Our study found that PARP1 inhibitors in combination with OXA have a powerful anti-tumor effect in gastric cancer patients without BRCA1 mutations." (PMID 34497808, 2021). "Moreover, INCENP revealed a medium correlation with PARP1 also in breast, liver, ovarian and stomach cancer." (PMID 31105872, 2019).